IL1A (interleukin 1 alpha)
Diseases named in the same sentence as IL1A in open-access papers (continued):
Sharing a sentence is not in itself a finding about the gene and the disease.
viral infection (continued). "Moreover, HPV vaccines have been associated with increased levels of cytokines (IL-2, IL-6, IL-1α, and IL-1β) and with the induction of IFN-γ-producing CD4+ and CD8+ T-lymphocytes, cytotoxic cells that clear viral infections." (PMID 38068369, 2023). "As these pro-inflammatory responses (IL-8 and IL-1A) are modulated as early immune responses during viral infections, earlier timepoints might have been more appropriate for analysis in the present study." (PMID 36992344, 2023). "The viral infection also led to common alterations in some genes and signaling pathways in both iM1φ and iM0φ cells, such as IL1A, IL1B, CCL7, chemokine-mediated signaling, viral protein interaction with cytokine–cytokine receptor, and Toll-like receptor signaling." (PMID 35440562, 2022). "Furthermore, IL1A, IL12B, DEFB4A, and CAMP, which are associated with the inflammatory response and inhibition of viral infection, were significantly more abundant in the HSV-1 epithelial keratitis patients than in the healthy control subjects." (PMID 32867704, 2020). "Poly-ICLC is one TLR3 agonist which is often combined with vaccine and cellular immunotherapies in order to induce type I interferons and mimic inflammatory response to systemic viral infection by amplification of interferons alpha and gamma as well as IL-1a and IL-6." (PMID 29157306, 2017). "Some viral-infection-related genes, such as Il1a and Srpk1, exhibited gains of stop codons, which may correlate with the ability of the AHR to serve as a pathogen carrier." (PMID 27172215, 2016). "Interleukin-1alpha (IL-1α), interleukin-1beta (IL-1β) and interleukin-18 (IL-18) have critical roles in the establishment of neutrophilic inflammation, which is commonly seen in airways viral infection and thought to be detrimental in respiratory disease." (PMID 23723976, 2013). "Normally, virus infection may enhance IL-1α, IL-1β and TNF-α expression that consequently inhibits virus replication." (PMID 23527143, 2013). "Moreover, increased bacterial adhesion may be mediated not only by virus infection but also by pro-inflammatory cytokines such as IL-6, IL-1α, and TNF-α, which upregulate receptors like ICAM-1, PAFr, and CEACAM1." (PMID 40520162, 2025). "IL-1α is more commonly associated with “sterile” inflammation that accompanies apoptotic cell death, and with the exception of adenovirus mediated inflammation has not been associated with pathology arising from viral infection." (PMID 23056330, 2012). "The results of our study demonstrate the importance of IL-1α and its cognate receptor, IL-1R1, to the induction of cigarette smoke-induced airway inflammation, and to the exacerbation of inflammatory processes following viral infection of smoke-exposed animals." (PMID 22163019, 2011). "Induced by a series of other cytokines as IL1A (IL1A fold regulation = 2.99), IL1B (IL1B fold regulation = 10.76), IL7, TNF (TNF fold regulation = 2.39), LPS or viral infections, CCL5 behaves like a proinflammatory cytokine." (PMID 40149697, 2025). "Only no statistically significant slight enhancements were observed for IL1A, the anti-inflammatory IL10, and the interferon-gamma (IFNG) which increases during a viral infection and in some circumstances, it can act as a pro-inflammatory molecule." (PMID 41573543, 2025). "Alternatively, this endothelial injury could be triggered by direct viral infection of vascular cells (though this possibility is uncertain, viral replication in non-respiratory tissues is commonly observed at post-mortem); or thrombin mediated activation of IL-1α." (PMID 33692097, 2021). "We observed increased level of inflammatory mediators (IL-1α, IL-1β, IL-6, MIP-1α (CCL3), MIP-1β (CCL4), RANTES (CCL5), MCP-1 (CCL2)) following H5N3 virus infection at 4, 8 and 20 hpi compared to cells infected with the H1N1/WSN, H5N2 and H9N2 viruses." (PMID 28558796, 2017).
viral infection (continued). "Levels of twelve cytokines and chemokines in the apical supernatant of hAECs were elevated following A(H7N9) virus infection, including GRO-α, MIP1-α, MIP1-β, SDF-1α, RANTES, IL-1α, IP10, IL-1RA, MCP1, IL-8, IL-6, and IL-1β." (PMID 28900138, 2017). "In dendritic cells of patients with COPD, OM-85 increased the secretion of IL-1α, IL-1β, IL-6 and TNF-α, which was regarded as a strengthening of the immune response during viral infection." (PMID 29182620, 2017). "Both IL-1α and IL-1β levels in the SCD animals were elevated at baseline, similar to levels eventually reached by these cytokines in WT animals after virus infection." (PMID 28256526, 2017). "In our study, levels of 12 cytokines and chemokines in the apical supernatant of hAECs were elevated following A(H7N9) virus infection, including GRO-α, MIP1-α, MIP1-β, SDF-1α, RANTES, IL-1α, IP10, IL-1RA, MCP1, IL-8, IL-6, and IL-1β." (PMID 28900138, 2017). "The levels of either gene expression or cytokine proteins (IL-1α, TNFα, IL-6, CXCL10, CCL5, CCL2, CCL3, CCL4, and CCL5) in RSV-infected PMФ are comparable to the H5N3 virus infection." (PMID 28558796, 2017). "In addition to allowing efficient BV transduction, wtBV has been shown to immunostimulate the release of inflammatory cytokines, including INFs, TNF-α, IL1A, IL1B and IL6 in mammalian cells and confer protection from lethal virus infection in mice." (PMID 31649751, 2019). "Notably, we found IL1α (a cytokine) and ISG15 (an interferon-induced protein) were up-regulated in SARS-CoV-2-infected HPAEpiC cells, which indicated some innate immune pathways were activated following viral infection." (PMID 33293527, 2020). "The levels of MIP-1β, IL-1α, G-CSF, and IL-9 were affected neither by MHV-1 viral infection nor Apta-1 treatment." (PMID 38474386, 2024). "Some markers of early virus-induced inflammation were not altered and we detected similar levels of IL1α, IFNβ or CCL2 in all mice one day after virus infection as a potential result of pattern-recognition receptor activation in infected cells." (PMID 39472590, 2024).
Stroke (56 papers, 2011 to 2025). Sudden impairment of blood flow to a part of the brain due to occlusion or rupture of an artery to the brain. "In the present study, we found a high prevalence of carotid atherosclerosis in the high-risk stroke population in China and also identified the associations of variants in IL1A rs1609682, PPARA rs4253655, and HABP2 rs7923349 with carotid atherosclerosis." (PMID 37292135, 2023). "An IL-1β haplotype in postmenopausal women and hypertensive persons, and an IL-1α haplotype in Koreans are associated with increased stroke risk." (PMID 32503645, 2020). "These pro-inflammatory cytokines (IL-1β and IL-1α) are involved in the underlying mechanism of various chronic inflammatory CNS conditions, such as stroke, Alzheimer’s disease, Parkinson’s disease, and epilepsy." (PMID 29334965, 2018). "In terms of stroke etiology, TT genotype and T allele frequencies of IL-1α-889 were more common among cases with LAA (cases with LAA versus controls: TT: 18.4% versus 10.1%, P < 0.05; T: OR = 1.442, 95% CI = 1.18–1.78, and P = 0.001)." (PMID 24063019, 2013). "Mice in which both IL-1α and IL-1β have been deleted (IL-1α/β double KO) have markedly reduced damage in response to experimental stroke caused by middle cerebral artery occlusion (MCAo)." (PMID 22206506, 2011). "This might have provided some mechanistic insights into the relationship between variants of the IL-1α and IL-1β genes and IS according to stroke etiology." (PMID 24063019, 2013). "The concentration of IL1α increased significantly 24 h after stroke (39.71 ± 15.86 pg/mL) (p < 0.05)." (PMID 40332314, 2025). "Preconditioning MSCs with IL-1α induced an anti-inflammatory, pro-trophic phenotype that enhanced their regenerative potential, with IL-1α-derived MSC-CM improving stroke outcomes when administered alongside thrombectomy." (PMID 40244116, 2025). "The increase in the gene expression of pro-inflammatory interleukin IL1α was observed 6 h after stroke induction compared to in the contralateral hemisphere (p < 0.05)." (PMID 40332314, 2025). "We determined the elevated gene expression of pro-inflammatory cytokines such as IL1α and IL1β and TNFα as soon as 6 h after stroke induction." (PMID 40332314, 2025). "Our study identifies for the first time a critical role for microglial IL-1α on post-stroke neurorepair and recovery, highlighting the importance of targeting specific IL-1 mechanisms in brain injury to develop effective therapies." (PMID 40110693, 2025). "Aging-associated SASP occurs due to multiple factors; targeting the main upstream pro-inflammatory regulator, IL-1α, one can better understand the cross interactions of the pro-inflammatory signaling cascade between stroke and SASP." (PMID 38543098, 2024). "TNFSF15 belongs to the tumor necrosis factor (TNF) ligand family induced by TNF and IL-1α, which plays an important role under disease conditions, such as cancer and stroke, by maintaining vascular and lymphatic vessel homeostasis." (PMID 36936375, 2023). "A previous study confirmed that genetic deletion of IL-1α and IL-1β in mammals leads to a substantial reduction in damage after experimental stroke." (PMID 36685518, 2022). "It has been reported that compared to controls, IS patients have higher IL-6, IL-8, and TNFα protein in plasma and lower IL-6, IL-8, TNFα, IL-1α, and IL-1β mRNA in leukocytes within 72 h after stroke." (PMID 36547090, 2022). "The expression of both IL-1α and IL-1β was dramatically elevated in the ischemic hemisphere 6-24 hours after stroke onset." (PMID 34248961, 2021). "Instead, post-stroke inhibition of IL-1α modulated cerebral injury by blunting endothelial activation and expression of adhesion molecules, thereby reducing penumbral mononuclear phagocyte content and related neurotoxic mediators such as MMPs." (PMID 33770265, 2021). "Further work investigating the efficacy of targeted delivery of IL-1α-primed MSCs in stroke is ongoing." (PMID 32862401, 2021).
Stroke (continued). "IL-1α has been shown to have brain protective qualities in mouse stroke models and promotes neurorepair when mice are treated with delayed administration of IL-1α." (PMID 34654436, 2021). "For example, in mouse ischemic stroke models, lymphocytes infiltrating into the whole stroke brain were complicated with inflammatory cytokines IL-1α, IL-1β, IFN-γ, TNF-α, and IL-6 at 2 weeks after stroke." (PMID 34421544, 2021). "Further it was observed that IL-1α levels increase within the brain in post-stroke animal models during angiogenic periods." (PMID 34654436, 2021). "In this study, the administration of αCM derived from IL-1α-primed MSCs was delayed to 24 h post-stroke." (PMID 31964413, 2020). "Conditioned medium from IL-1α-primed MSCs or vehicle was administered at the time of reperfusion or at 24 h post-stroke by subcutaneous injection." (PMID 31964413, 2020). "We showed previously that TNF and IL-1β and IL-1α, IL-1β, IL-1Ra are produced by subsets of microglia in experimental stroke." (PMID 32503645, 2020). "We therefore compared parallel tissue sections from two stroke cases stained for IL-1α, IL-1β, IL-1Ra, TNF, TNFR1, and TNFR2." (PMID 32503645, 2020). "IL-1α-primed MSC-derived conditioned medium treatment at the time of stroke led to a ~ 30% reduction in lesion volume at 48 h and was associated with modest improvements in body mass gain, 28-point neurological score and nest building." (PMID 31964413, 2020). "Taken together, we were able to use IL-1α in combination with our recently developed IA drug delivery and stroke model as a proof of concept for giving potentially life-saving drugs with a safer drug delivery mechanism." (PMID 31727174, 2019). "IL-1α is one of the first cytokines upregulated after stroke, and we recently demonstrated that IL-1α treatment of brain endothelial cells showed pro-angiogenic effects in vitro." (PMID 31727174, 2019). "Sub groups of the mice were treated with either saline or Il-1α, wherein the drug was administered either acutely (immediately after surgery) or subacutely (on the third day after stroke)." (PMID 31727174, 2019). "Such is the potency of IL-1α in this context, downstream targets of IL-1α are also being studied as potential neurotherapeutic molecules in stroke." (PMID 31293586, 2019). "In stroke, brain IL-1α expression precedes that of IL-1β and occurs predominantly in microglia localized to focal neuronal and BBB injury in this acute period." (PMID 31727174, 2019). "Fortunately, post-stroke IA delivery allowed us to both administer less IL-1α, and to deliver IL-1α in a stroke-targeted fashion, collectively reducing hemodynamic side effects." (PMID 31727174, 2019). "Serum inflammatory factors interleukin-1-α and interleukin-6 increased after stroke in all groups, compared to the sham group in which this rise was significant in IL-1α." (PMID 30719249, 2018). "Our data contradicts findings arguing that IL-1α is the predominant form of IL-1 following stroke, but supports the view that IL-1α plays an important role in stroke pathology, by strengthening in vitro findings of IL-1α in platelets." (PMID 26860727, 2016). "Conversely, disruption of IL-1α and β activity in IL-1α/β knockout (KO) mice resulted in markedly reduced (70%) infarct volumes following experimental stroke." (PMID 25705177, 2015). "In this study we sought to determine the spatial distribution of IL-1α and IL-1β in the mouse brain early (4 h) and late (24 h) after stroke induced by MCAo." (PMID 22206506, 2011). "Here we show that IL-1α and IL-1β have different spatio-temporal expression profiles in the brain after experimental stroke, with early microglial IL-1α expression (4 h) and delayed IL-1β expression in infiltrated neutrophils and a small microglial subset (24-72 h)." (PMID 40110693, 2025).
Stroke (continued). "However, microglial IL-1α knock out (KO) mice showed reduced peri-infarct vessel density and reactive astrogliosis at 14 days post-stroke, alongside long-term impaired functional recovery." (PMID 40110693, 2025). "After a stroke, microglia preferentially respond to pathological stimuli and secrete IL-1α, TNF-α, and C1q after activation, triggering reactive signals of astrocytes through soluble and membrane-bound signaling molecules, inducing their transformation into pro-inflammatory astrocytes." (PMID 40289984, 2025). "In addition to Il6, we also observed downregulation of Il1a and Il1b in male stroke brains, and downregulation of Il1r1 in female stroke brains upon genetic ablation of MMP-3." (PMID 39000490, 2024). "Although IL-1α is known as a pro-inflammatory factor responsible for inducing inflammation, it has been reported to work locally through another mechanism of neuroprotection and neurogenesis during post-stroke inflammation." (PMID 36618411, 2022). "Unlike the aged-female group, IL-1α, a proinflammatory cytokine that has been implicated in neuroinflammatory progression post-stroke, was significantly decreased in male rats treated with WBV." (PMID 36062148, 2022). "Furthermore, we reported that post-ischemic treatment with antibodies neutralizing IL-1α and β reduce stroke size and improve post-stroke neurological deficit in mice undergoing tMCAO, by reducing post-ischemic BBB impairment through different pathways." (PMID 33770265, 2021). "Hence, it is essential to confirm the benefit of IL-1α priming in a relevant in vivo paradigm with an extensive characterisation of the post-stroke behavioural repertoire, as investigated here in a mouse model of middle cerebral artery occlusion." (PMID 31964413, 2020). "Acute post-stroke IV or IA IL-1α administration resulted in comparable significant reductions in ischemic infarct volume, fewer apoptotic cells, improved functional recovery, and decreased neuroinflammatory activation, the latter with IA treatment being more effective than IV treatment." (PMID 31727174, 2019). "As a proof of concept, we first investigated whether IL-1α could impart protection to neurons undergoing the in vitro stroke analogue oxygen glucose deprivation (OGD) or using an in vitro model of post-stroke toxicity, exposure to NMDA." (PMID 31727174, 2019). "To test this hypothesis, we used perlecan hypomorph (pln KO, expressing approximately 10% of normal physiological levels of perlecan) mice in post-stroke IL1α administration experiments." (PMID 31727174, 2019). "We next investigated the therapeutic potential of acute IL-1α administration in experimental stroke in vivo, as well as whether it might also represent an attractive candidate for IA drug delivery using our recently developed IA drug delivery in stroke model." (PMID 31727174, 2019). "While the potential involvement of IL-1R in IL-1α’s therapeutic effects remains to be confirmed in vivo, our in vitro results suggest a complex mechanism of action that could shed light on why IL-RA stroke therapy has met with mixed success." (PMID 31727174, 2019). "Therefore, although we observed neurogenesis in the SVZ, other brain region-derived stem cells and their roles in the post-stroke brain, especially following IL1α treatment needs to be explored." (PMID 31727174, 2019). "As our previous work suggested that IL-1α could promote brain angiogenesis in vitro, we also investigated the potential reparative effects of IL-1α in the context of stroke in vivo." (PMID 31727174, 2019). "We next investigated whether delayed/subacute IL-1α could also impact post-stroke neurogenesis, an additional reparative process." (PMID 31727174, 2019). "This suggests that the animals tolerate IL-1α up to 105-fold our chosen IV post-stroke dose." (PMID 31727174, 2019). "We have recently described the angiogenic effects of IL-1α in post-stroke angiogenesis in vitro." (PMID 31727174, 2019).